ZEB1 (zinc finger E-box binding homeobox 1)
Diseases named in the same sentence as ZEB1 in open-access papers (continued):
Sharing a sentence is not in itself a finding about the gene and the disease.
glioma (continued). "In glioma, miR-200c and miR-141 were found to synergistically suppress ZEB1 to inhibit glioma cell growth and migration." (PMID 36279099, 2023). "Accordingly, western blotting showed that overexpression of LIMD1-AS1 resulted in higher Cyclin B1, Bcl-2, N-cadherin, and ZEB1 expression at protein levels in SF126 glioma cells." (PMID 37385987, 2023). "Accordingly, Sun and co-workers showed the regulation of TF expression by the miR200a/ZEB1 axis in glioma cells." (PMID 38201433, 2023). "PDGFA/PDGFRA signaling has been shown to induce EMT through stimulation of ZEB1, thereby promoting glioma tumor growth and invasion and GSCS stemness." (PMID 36829235, 2023). "Suppression of PPP3CC by ZEB1 contributes to nuclear factor‐kappa B activation and promotes the growth and invasion of glioma cells." (PMID 34739189, 2022). "The interaction between miR-200c and miR-141 decreased EMT as well as glioma cell growth and aggression by downregulating ZEB1." (PMID 36402997, 2022). "The expression of ZEB1 was enhanced in IDH1/2-mutant gliomas, and IDH1/2-mutant gliomas exhibited significantly lower values of ZEB1 protein." (PMID 36402997, 2022). "Taken together, our results demonstrate that quercetin inhibited migration and invasion of human glioma cells by suppressing GSK3β/β-catenin/ZEB1 signaling." (PMID 36386155, 2022). "Recurrences are significantly more common in GBM patients with high ZEB2 levels, and glioma cells become more invasive when activated nuclear factor-B induces ZEB1 expression." (PMID 35163279, 2022). "One of the major factors involved in the disruption of intercellular connections is zinc finger E-box binding homeobox 1 (ZEB1), which affects cadherins, the main class of cell adhesion molecules in glioma cells." (PMID 35448036, 2022). "LncRNA was known to function as a ceRNA to regulate ZEB1 via multiple pathways in regulation of EMT process of glioma cells." (PMID 35912271, 2022). "In conclusion, a variety of lncRNAs can regulate the EMT process of glioma through ZEB1, which is closely related to tumor metastasis and drug resistance." (PMID 35912271, 2022). "ZEB1 plays an important role in glioma invasion, and the expression level of ZEB1 is associated with poor prognosis in patients with GBM." (PMID 35448036, 2022). "miR-876-5p plays an important role in the lncHOXC-AS2 (LncRNA HOXC cluster antisense RNA 2)-miR-876-5p-ZEB1 signaling pathway to promote EMT in gliomas." (PMID 36479040, 2022). "E-cadherin protein expression is downregulated upon binding of ZEB1 to its promoter, resulting in glioma cell separation and migration." (PMID 36479040, 2022). "A link between isocitrate dehydrogenase 1 (IDH1) and ZEB1 expression has been reported in lower-grade glioma." (PMID 36402997, 2022). "Previously, RBP ZEB1 facilitated hypoxia-mediated epithelial-mesenchymal transition in glioma cells." (PMID 33634155, 2021). "In this study, the expression of H19, miR-200a, CDK6 and ZEB1 as well as their interaction in glioma have been investigated." (PMID 34796112, 2021). "The results suggested that up-regulation of miR-200a was able to inhibit the invasion and migration of glioma cells, which were abolished by overexpressed ZEB1." (PMID 34796112, 2021). "In conclusion, our results revealed the interaction of H19, miR-200a and CDK6/ZEB1 in glioma cells, which can affect tumor progression." (PMID 34796112, 2021). "ZEB1 was also found to have an inhibitory transcriptional function by binding to the promoter region of LIF to suppress its expression in glioma cancer stem cells, which inspired us to investigate the role of HIF1α and the ZEB1/LIF axis in hepatic I/R injury." (PMID 32996684, 2020). "Subsequently, Wnt/β-catenin pathway enhances the expression of Snail, TWIST and ZEB1 which regulate the EMT process, causing an increase in the invasion and migration of glioma cells." (PMID 32154177, 2020).
glioma (continued). "For example, linc00645 enhanced transforming growth factor beta (TGF-β)-triggered epithelial mesenchymal transition (EMT) through regulation of microRNA-205-3p (miR-205-3p) and zinc finger E-box binding homeobox 1 (ZEB1) in glioma." (PMID 32322669, 2020). "Here, we found that overexpressing RIOK2 elevated the expression of N‐cadherin, β‐catenin, Twist1, fibronectin and ZEB‐1, whereas the miR‐4744 mimics treatment showed the opposite effects in glioma cells." (PMID 32125767, 2020). "Our findings are in agreement with published report whereby loss of NF1 by shRNA promoted glioma cell invasion and upregulation of EMT markers such as vimentin, SNAI, TWIST1, ZEB1, and ZEB2." (PMID 30967630, 2019). "In particular, miR-590-3p has also been found to be downregulated in glioma and impedes the malignant development of glioma cells through targeting ZEB1 and ZEB2." (PMID 31186064, 2019). "As reported in glioma cell lines, TGFβ is an inducer of ZEB1-dependent mesenchymal trans-differentiation coupled to enhancement of their invasion capability." (PMID 31905754, 2019). "Studies that deal with larger patient cohorts would be more informative in determining the role of ZEB1 at least in gliomas." (PMID 32309604, 2018). "In human specimens it was found that with increasing grade of glioma there was higher expression of ZEB1 and ZEB2." (PMID 32309604, 2018). "They further validated these findings and found increased expression of ZEB1 mRNA in IDH1-mutant grades II–III gliomas, and ZEB1 protein expression was more pronounced in these tumors." (PMID 32309604, 2018). "Another set of in vitro and in vivo experiments in several types of glioma cell lines, including U251 and A172, showed that ZEB1 was highly expressed across the lines and that when knocked down smaller tumors were formed." (PMID 32309604, 2018). "Yet we still appreciate the complexity of ZEB1 which even conflicts with our own data, as we have previously shown that ZEB1 is involved in the invasive process in glioma stem cells." (PMID 30705664, 2018). "While the tumor suppressive role of ZEB1 remains controversial and is still in its infancy, ZEB1 research as it pertains to gliomas and other cancers is undeniably complex and still has much that remains to be unveiled." (PMID 32309604, 2018). "This study also showed that ZEB1 is increased in gliomas and positively correlates with progression and inversely correlates with TET2 expression." (PMID 32309604, 2018). "One of the first findings were in lower grade gliomas (LGGs) where bioinformatic analysis found increased expression of ZEB1 which positively correlated with a substantial increase in overall survival (OS)." (PMID 32309604, 2018). "Univariate and multivariable overall survival analyses with ZEB1 alone and IDH/ZEB1 in addition to clinical variables in patients with grade II/III gliomas." (PMID 30705664, 2018). "In this review we address the complexity and discrepancies with respect to the functional roles of ZEB1 in cancer, with a focus on brain cancer of both low and high-grade gliomas." (PMID 32309604, 2018). "MALAT1 promotes cell proliferation by sponging miR-101 and increases cell resistance to temozolomide (TMZ) by regulating ZEB1 in glioma." (PMID 29552296, 2018). "We show that serglycin can promote aggressiveness in glioma by increasing the expression of ZEB-1 and vimentin." (PMID 28445977, 2017). "ZEB1 is active in hypoxic pseudopalisades that surround necrotic areas and exposure to low oxygen augments invasive properties of glioma cells through the induction of EMT activators." (PMID 28556516, 2017). "In contrast, we have observed ZEB1 deletions in more than 50% of GBMs and 15% in low grade gliomas (grade II and grade III) with frequent LOH." (PMID 28246407, 2017).
glioma (continued). "In general terms, it seems that, in glioma cells, stemness and mesenchymal phenotype are closely linked: knockdown of genes directly involved in EMT, such ZEB1, also causes inhibition of stem cell regulators like Sox2 and Olig2." (PMID 29261132, 2017). "Investigation of markers related to cancer progression in glioma cells co-cultured with MCs show a significant induction of ZEB1 and vimentin accompanied by a positive induction of glioma cell proliferation in co-culture with MCs." (PMID 28445977, 2017). "We analyzed protein expression of ZEB1 by immunohistochemistry in a panel of human gliomas of different WHO grade and a tissue microarray (TMA) of 243 high grade glioma samples and performed an unbiased, single-cell level classification." (PMID 28945795, 2017). "As we show in IDH-mutant glioblastomas and glioma cell lines, however, ZEB1 appears to be expressed uniformly by the entire tumor cell population." (PMID 28945795, 2017). "While tumor cells in glioma consistently express ZEB1, we observed mutually exclusive staining with markers of immune cells (CD45, CD68, Iba1, HLA-DR)." (PMID 28945795, 2017). "Targeting the Sonic Hedgehog (SHH) pathway at the level of Smoothened suppresses glioma malignancy by upregulating miR200 and consequently blocking ZEB1." (PMID 28556516, 2017). "This surprisingly ubiquitous and robust expression pattern of ZEB1 in glial tumors challenges the canonical concept of ZEB1 as a marker of EMT and tumor progression." (PMID 28945795, 2017). "The current study provides an in situ characterization of ZEB1 at single cell resolution in human gliomas." (PMID 28945795, 2017). "Statistical analysis of the expression of serglycin and ZEB1 in high-grade glioma showed a positive correlation." (PMID 28445977, 2017). "Consistent with our observation of poor patient survival due to ZEB1 deletion; patients with low ZEB1 expression resulted in shorter patient survival in both lower grade gliomas (***P < 0.0001) and GBMs (*P = 0.002)." (PMID 28246407, 2017). "In non-tumor brain samples obtained from epilepsy surgery, we found that the ZEB1-positive fraction is expression is significantly lower (linear regression, p = 0.0005), especially in normal white matter where glial tumor usually reside." (PMID 28945795, 2017). "As a validation, we compared ZEB1 expression in gliomas vs. normal brain tumors in public transcriptomic datasets from several studies and found higher ZEB1 mRNA expression in glial tumors compared to normal brain controls." (PMID 28945795, 2017). "ZEB1 protein expression in glioma stem cell lines was compared to their parental tumors with respect to gene expression subtypes based on RNA-seq transcriptomic profiles." (PMID 28945795, 2017). "In our study, we found that reduced LINC00461 expression reduced expression levels of some EMT markers (N-cadherin and ZEB1) and several other factors related to glioma “stemness” (CD44, SOX2, Nestin)." (PMID 29137410, 2017). "NF-κB binds to the ZEB1 promoter in glioma cells in response to connective tissue growth factor, which is important for glioma invasion." (PMID 28598356, 2017). "Specifically, we address how ZEB1 exerts its effects on key malignant processes in glioma, i.e. invasion, tumourigenesis and therapy resistance." (PMID 23818228, 2013). "TGF-β-induced epithelial-mesenchymal transition by regulating miR-205-3p-ZEB1 axis in glioma." (PMID 38874022, 2024). "miR-141-5p inhibits glioma cell growth and migration by repressing ZEB1 expression." (PMID 37705830, 2023). "It has been reported that WNT/β-catenin and ZEB1 play an essential role in glioma invasion and EMT." (PMID 36386155, 2022).
glioma (continued). "In summary, miR-200a could suppress the invasion/migration of glioma cells via directly binding to ZEB1." (PMID 34796112, 2021). "Moreover, overexpression of miR-200a resulted in down-regulation of ZEB1 and further inhibited malignant phenotype of glioma cells." (PMID 34796112, 2021). "Altogether a regulatory axis consisting of OR7E156P, miR-143, and HIF1A, was identified which is deregulated in glioma, and the process of the OR7E156P/miR-143/HIF1A axis modulating glioma cell invasion through ZEB1 and HUVEC tube formation through VEGF was demonstrated." (PMID 34422645, 2021). "Furthermore, the biological effects of H19, miR-200a, CDK6 and ZEB1 in glioma tissues/cells were also elucidated in vivo and in vitro." (PMID 34796112, 2021). "In consistence with these findings, ZEB1 expression was increased in glioma cell lines." (PMID 34796112, 2021). "ZEB1 has been reported to increase in gliomas and positively correlate with tumor progression." (PMID 34249910, 2021). "A low TET2 level in MA cells could be due to low gene dosage, but could also involve other mechanisms such as repression by ZEB1 as reported in glioma; MA cells express a high level of ZEB1 as a part of their EMT program." (PMID 31217902, 2019). "IDH1/2 somatic mutations are associated with lower normalized mean diffusion kurtosis, increased ZEB1 expression in lower-grade gliomas, preoperative seizures in gliomas, CpG methylator phenotype (CIMP), global hypermethylation, younger age, secondary glioblastoma, and increased overall survival." (PMID 29556922, 2019). "A similar conflict of ZEB1 duality can be found in gliomas as seen in several recent studies." (PMID 32309604, 2018). "Finally, a study was performed to try and characterize ZEB1 at the level of single cell resolution in human gliomas with respect to clinical and molecular traits." (PMID 32309604, 2018). "However, recent studies have emerged indicating the possibility of a novel tumor suppressive role of ZEB1 in gliomas." (PMID 32309604, 2018). "Our previous demonstration that ZEB1 is a negative regulator of LIF, a gene that induces glioma stem cell propagation, suggests that the deletion of ZEB1 may impart more stemness to tumors that lose ZEB1 expression." (PMID 30705664, 2018). "For example, Neswick and colleagues found higher ZEB1 levels in IDH-mutant gliomas." (PMID 28945795, 2017). "We thus conclude that ZEB1 is robustly expressed in glial tumor cells." (PMID 28945795, 2017). "An increase in ZEB1 expression was also detected in human high-grade glioma TMAs." (PMID 28445977, 2017). "It has previously been reported that ZEB1 expression is higher in IDH mutant lower grade glioma." (PMID 28945795, 2017). "In over 50% of glioma cases, we observed a deletion that included ZEB1 on chromosome 10." (PMID 28246407, 2017). "ZEB1 is widely expressed in glial tumors, but in a highly variable fraction of cells." (PMID 28945795, 2017). "ZEB1 is associated with malignancy in glioma and analysis of GBM patient specimens demonstrated that proinflammatory cytokines, such as CXCL12, IGFBP2, IL-1ß, TNF-a and MIF, correlate significantly with ZEB1 expression in tumor specimens." (PMID 28445977, 2017). "Indeed, high-grade glioma TMAs immunostaining for ZEB1 revealed abundant expression of this protein, as well as a positive correlation between ZEB1 and serglycin levels (ρ < 0.01)." (PMID 28445977, 2017). "Even though a recent study suggests an enrichment in expression of EMT-related genes in tumor-associated macrophages in gliomas, we showed that immune cells are consistently ZEB1-negative." (PMID 28945795, 2017). "As CD44 is associated with glioma stem cells and recent studies indicate a reciprocal link between CD44 and ZEB1 we tested whether ZEB1 may be a substitute marker for CD44." (PMID 28445977, 2017).
glioma (continued). "Because the ZEB1-positive population was coincident with the distal-most, invading tumour cells, we hypothesised that ZEB1 may have a regulatory role in glioma invasion, and attempted to determine its specific functions in glioblastoma." (PMID 23818228, 2013). "Given the low prevalence of E-cadherin in glioma, we asked whether ZEB1 could affect glioma invasion through other mechanisms." (PMID 23818228, 2013). "Additionally, targeting ZEB1 has been shown to reduce bevacizumab-resistant glioma phenotypes." (PMID 40160462, 2025). "Similarly, glioma cells with ZEB1 expression induced by nuclear factor-β were more invasive." (PMID 35562862, 2022). "Similarly, our results indicated that overexpressed miR-200a could suppress the migration and invasion of glioma cells by targeting ZEB1." (PMID 34796112, 2021). "In addition, transcription factor zinc finger E-box binding homeobox 1 (ZEB1) upregulates the level of X-ray repair cross complementing 4 (XRCC4) expression via the SBF2-AS1/miR-151-3p axis to enhance resistance to temozolomide in glioma cell lines." (PMID 34372871, 2021). "Transcription of TET2 may be repressed by zinc finger E-box-binding homeobox 1 (ZEB1) in gliomas." (PMID 33842321, 2021). "ZEB1 could be a putative target gene of miR-200a in glioma cells." (PMID 34796112, 2021). "Moreover, the novel feedback loop involving H19/miR-200a/CDK6 and ZEB1 could regulate the proliferation, invasion and migration of glioma cells." (PMID 34796112, 2021). "It was also shown that in IDH-mutant glioblastomas and glioma cell lines there was uniformity in ZEB1 expression which led them to believe that this ubiquitous and robust expression pattern challenges the canonical concept of ZEB1 as a marker of EMT and tumor progression." (PMID 32309604, 2018). "In addition, the expression of serglycin and ZEB-1 is positively correlated in high-grade glioma." (PMID 28445977, 2017). "In this study, we show that the invasive ability of glioma cells was decreased following CBX7 overexpression and CBX7 overexpression was associated with Wnt/β-catenin pathway inhibition, which also decreased downstream expression of ZEB1, a core epithelial-to-mesenchymal transition factor." (PMID 28388562, 2017). "Furthermore, silenced ZFAS1 could impair migration and invasion by inhibiting the epithelial–mesenchymal transition through reducing the expression of MMP2, MMP9, N-cadherin, Integrin β1, ZEB1, Twist, and Snail as well as increasing E-cadherin level in glioma." (PMID 29245995, 2017). "Our data indicated that ZEB1 expression is lost in a significant number of glioma patients, and that the cause of ZEB1 loss is due in large part to heterozygous deletions in both GBMs and lower grade gliomas with frequent LOH in at least 20% of glioma patients." (PMID 28246407, 2017). "On the other hand, the overexpression of the oncogenic factor KAI1 C-terminal interacting tetraspanin (KITENIN) promotes EMT in glioma cells by increasing the expression of EMT markers, such as N-cadherin, ZEB1, ZEB2, SNAIL, and Slug." (PMID 41141394, 2026). "SRGN-expressing glioma cells after co-culture with mast cells further enhance their expression of SRGN, CD44, CXCL-10, CXCL-12 and TNFα as well as EMT-related genes ZEB-1 and vimentin." (PMID 38672477, 2024). "The expression of SNAIL, SLUG, TWIST, ZEB1, and ZEB2 enables glioma cells to shift toward a mesenchymal phenotype." (PMID 38092725, 2023). "Hypoxia-induced glioma cells upregulated lncRNA HOTTIP and sponge inhaled endogenous miR-101, resulting in increased ZEB1 expression and promoting EMT process." (PMID 35912271, 2022). "LncRNA UCA1 partially rescued the inhibitory effect of miR-204-5p on ZEB1 via binding and inhibiting miR-204-5p, which promoted the EMT process of glioma cells." (PMID 35912271, 2022). "The ZEB proteins ZEB1 and ZEB2 are another notable family of transcription factors that mediate EMT in a variety of tumors, including gliomas." (PMID 35163279, 2022).